CXCL12 (C-X-C motif chemokine ligand 12)
Diseases named in the same sentence as CXCL12 in open-access papers (continued):
Sharing a sentence is not in itself a finding about the gene and the disease.
glioma (continued). "Additionally, CXCL12 was shown to selectively attract and positively stimulate the migration of glioma cells which exclusively upregulated the expression of CXCR4 receptors." (PMID 29113105, 2017). "A link between MCs and the CXCL12 in glioma TME had previously been established." (PMID 28445977, 2017). "Thus, the inhibition of CXCR4 (and its interaction with CXCL12) is a potential target for inhibiting glioma cell invasion and recurrence." (PMID 27863376, 2016). "Additionally, IFF has been shown to enhance glioma invasion through CXCR4/CXCL12-dependent autologous chemotaxis." (PMID 26560447, 2015). "The increase of CXCR7 expression in microvascular endothelial cells during hypoxia favors CXCL12-induced glioma cell migration facilitating the binding of CXCL12 to endothelial cells and the activation of CXCL12-mediated cell crossing through endothelium." (PMID 24904289, 2014). "Among these factors, stromal cell-derived factor-1 (SDF-1/CXCL12) is known to be involved in glioma invasion by recruiting macrophage or T-regulatory cell migration to the peritumoral area, by cross-talking with endothelial cells, or by mobilizing hematopoietic stem cells and progenitor cells." (PMID 23940516, 2013). "Hence, we propose that the MC accumulation within the gliomas is, at least partly, explained by a glioma-driven expression of CXCL12, combined with strong expression of CXCR4 within the brain tumor MC population." (PMID 21949886, 2011). "We therefore analyzed the gliomas for expression of CXCL12 and the endothelial cell marker CD31." (PMID 21949886, 2011). "Moreover, we present evidence suggesting that tumor-associated vessels produce SCF that drives MC proliferation and that MC chemotaxis in gliomas involves interaction between CXCL12 and CXCR4." (PMID 21949886, 2011). "Additionally, glioma cells also secrete CXCL12, probably leading to the proliferation and neovascularization of glioma through the autocrine/paracrine mechanism involved in the CXCL12/ CXCR4 receptor ligand system." (PMID 34764346, 2021). "This trial aimed to evaluate the efficacy of Plerixafor in treating patients with newly diagnosed high-grade glioma, leveraging its ability to disrupt TAM recruitment mediated by the SDF-1/CXCL12 axis." (PMID 38732975, 2024). "In the glioma microenvironment, microglia can be recruited by gliomas through chemoattractants such as CCL5, CCL2, CX3CL1, and CXCL12, and can penetrate the tumor." (PMID 38549161, 2024). "SRGN-expressing glioma cells after co-culture with mast cells further enhance their expression of SRGN, CD44, CXCL-10, CXCL-12 and TNFα as well as EMT-related genes ZEB-1 and vimentin." (PMID 38672477, 2024). "We also demonstrated colocalization of CXCL12 with CD31+ endothelial cells and GFAP+ tumor (glioma) cells, in particular, identifying these cell populations as important sources of CXCL12." (PMID 38806504, 2024). "In these immunostimulators genes, CXCR4, CXCL12 belonged to Chemokines and chemokine receptors, were also positively correlated with IGFBP5 expression in glioma." (PMID 38164271, 2024). "Chemoattractants such as MCP-1 (CCL2), MCP-3 (CCL7), SDF-1 (CXCL12), CX3CL1, POSTN, GM-CSF, M-CSF (CSF-1) and EGF produced by glioma cells actively recruit TAMs and thus promote tumor growth." (PMID 37705736, 2023). "The CXCL12/CXCR4 signaling pathway is activated in GBM and is critical for sustained glioma invasion, enhanced angiogenesis, and glioma stem cell migration." (PMID 37626511, 2023). "This distinction highlights the complex role of the trio CXCL12/CXCR4/CXCR7 in the bidirectional interaction between astrocytes and glioma cells." (PMID 38293652, 2023). "Co-culture of mast cells with glioma cells induces the expression of serglycin, CD44, ZEB1, vimentin, CXCL10, CXCL12, and TNF-α in glioma cells and IL-6 and CXCL1 in mast cells, creating an inflammatory milieu that induce glioma cell aggressiveness." (PMID 35494005, 2022).
glioma (continued). "The cross-talk between Notch1 signaling and CXCL12/CXCR4 system contributes to the progression and recurrence of GBM by promoting the self-renewal and invasion of glioma stem cells." (PMID 33552592, 2021). "This review also highlights ACKR3 as a multifaceted player in almost every of these glioma-related cellular processes and subtypes and prompts researchers in the field to further apprehend the subtleties of the CXCR4/ACKR3/CXCL12 triad in glioma." (PMID 35008294, 2021). "GAMs-attracting chemokines and cytokines secreted by glioma cells, which suppress immune cells, include CCL2, CXCL12, CSF-1, and MIF." (PMID 32194542, 2020). "Even if CCL2 is believed to be the major recruiter of TAMs in gliomas, other factors like CX3CL1, CXCL12, M-CSF and GM-CSF can mobilize TAMs into brain tumor areas, and become relevant under Ccr2-deficiency." (PMID 32668709, 2020). "CXCL12, also known as stromal derived factor 1 (SDF-1), a chemokine, promotes TAM recruitment in high-grade gliomas." (PMID 32765498, 2020). "Our finding of low CXCL12 levels in GBM patients seems to conflict with literature data, where CXCL12 levels allegedly correlate positively with glial tumor progression." (PMID 31428150, 2019). "We previously showed using an agent based model that heterogeneous populations of glioma cells are exquisitely sensitive to small changes in CXCR4 and CXCL12 co-expressing cells, leading to enhanced flow response via this autologous chemotaxis mechanism." (PMID 30451884, 2018). "In summary, recruitment and subsequent M2 polarization of GAMs has been shown to be mediated by multiple glioma cell-derived chemoattractants such as MCP-1 (CCL2), SDF-1 (CXCL12), M-CSF (CSF-1), GM-CSF, and EGF." (PMID 29389898, 2018). "Stromal-derived factor-1 (SDF-1/CXCL12) is another chemokine produced by hypoxic and invasive brain tumors that promote GAM recruitment in glioma microenvironment." (PMID 28346397, 2017). "Expression analysis of cytokines secreted by glioma cells co-cultured with MCs, revealed a significant increase in expression of CXCL10, CXCL12 and TNF-α." (PMID 28445977, 2017). "A number of signalling pathways that include autocrine components, such as TGFalpha/EGF/EGFR, PDGF/PDGFR, HGF/SF and CXCL12/CXCR4 ligand/receptor systems, have been identified in glioma and glioblastoma." (PMID 29149169, 2017). "Several reports demonstrated a correlation between high levels of CXCL12 and CXCR4 and tumor malignancy in different tumor types, including gliomas." (PMID 28423060, 2017). "Moreover, in gliomas characterized by high vasculogenic potential, the incorporation of EPCs into blood vessels was associated with CXCL12 secretion, whereas the CXCR4 antagonist AMD3100 abrogated the ability of CXCL12 to trigger EPC incorporation into the tumor vasculature." (PMID 29240722, 2017). "Since CXCL12 can increase tumor cell survival, knocking down CXCR4 would lead to an increase in glioma cell death." (PMID 27863376, 2016). "In these perinecrotic areas (“pseudopalisading” necrosis), characterized by high cellularity due to the powerful invasion of glioma cells, CXCR4 and CXCL12 co-localize in the same tumor cells." (PMID 24904289, 2014). "A role for CXCL12 modulation of CXCR4 and CXCR7 was identified for most of the brain tumors including gliomas, meningiomas and even pituitary adenomas that frequently overexpress these receptors." (PMID 24904289, 2014). "CXCL12/SDF-1 and its receptor CXCR4 have been shown to promote glioma stem cell-mediated VEGF production and tumour angiogenesis via PI3K/AKT signalling." (PMID 24971349, 2014). "In agreement with a role of the CXCL12/CXCR4 axis in promoting MC migration into the tumors, mMCP-6 positive MCs in both Ntv-a Arf−/− and Gtv-a Arf−/− mouse gliomas were frequently (with an average of 90%) CXCR4 positive." (PMID 21949886, 2011).
glioma (continued). "We analyzed gliomas for expression of CXCL12 and CXCR4 and found abundant expression of CXCL12 in both Ntv-a- and Gtv-a Arf−/− gliomas and there was also a clear expression of CXCR4 in the same samples." (PMID 21949886, 2011). "Additionally, TGF‐b as well as stromal cell‐derived factor‐1/CXC chemokine ligand 12 (SDF‐1a/CXCL12) directed migration of adult hematopoietic stem and progenitor cells toward glioma cells in vitro and their homing to experimental gliomas in vivo." (PMID 41498028, 2025). "Glioma and MSCs have been shown to secrete various factors, such as stromal cell-derived factor 1 (SDF-1, also known as CXCL12), VEGF, PDFG, endothelial cell growth factor (EGF), TGF-β1, interleukin 8 (IL-8), and the MCP1 protein, which contribute to tumor tropism." (PMID 38607056, 2024). "The CXCL12 expression in datasets from TCGA-glioblastoma and CGGA-mRNA-325 indicated elevated levels of CXCL12 in glioblastoma compared with normal tissues and in recurrent gliomas compared with treatment-naïve gliomas." (PMID 38898023, 2024). "Gliomas help recruit TAMs to the TME by secreting various chemokines, including monocyte chemoattractant proteins (MCP-1/CCL2 and MCP-3), C-X-C motif chemokine 12 (CXCL12), colony-stimulating factor 1 (CSF-1), lysyl oxidase (LOX), and glial cell-derived neurotrophic factor (GDNF)." (PMID 38254796, 2024). "CXCL12 has higher affinity for the receptor CXCR7 whose high expression correlates with poor glioblastoma patient survival and similarly to CXCR4 activation, triggers glioma proliferation and invasion." (PMID 38293652, 2023). "CXCL12 induces the invadopodia formation and the expression of membrane type-2 matrix metalloproteinase (MT2-MMP), which degrades the surrounding ECM and is involved in glioma invasion." (PMID 35204054, 2022). "It has been shown that the inhibition of CXCL12/CXCR4 signaling pathway, in combination with radiotherapy, decreased myeloid cells' infiltration; delayed tumor progression and ultimately led to anti-glioma immunological memory." (PMID 36186781, 2022). "On the other hand, glioma-cells release chemoattractant molecules that recruit TAMs and promote tumor growth: CCL2, CCL7 (or MCP-3), IL-33, GDNF (Glial cell line-derived neurotrophic factor), MCP-1 (CCL2), SDF-1 (CXCL12), CSF-1 (M-CSF), GM-CSF, and EGF." (PMID 35269652, 2022). "CXCL9, CXCL10, CXCL11, CXCL12, and CXCL14 were filtered as main contributors of glioma progression." (PMID 34603309, 2021). "Moreover, CXCL12 and its receptor CXCR4 have been shown to promote VEGF production mediated by glioma stem cells and tumor angiogenesis via PI3K/AKT signaling." (PMID 32456359, 2020). "The mechanism underlying the tropism of MSCs for gliomas has not been fully elucidated, but numerous chemotactic factors have been implicated in this process, including VEGF, SDF-1/CXCL12, and IL-8." (PMID 32942567, 2020). "It was shown that pattern of CXCL12 and CXCR4 expression may be also a predictive factor of glioma recurrence after its total resection." (PMID 32456359, 2020). "Our data suggested that FTY720 can block the cross-talk between glioma and GAMs by increasing microglial CXCR4 internalization rather than by affecting CXCL12 secretion by glioma." (PMID 32194542, 2020). "Targeting CXCL12/CXCR4 autocrine/paracrine loop could inhibit the survival and proliferation of glioma stem cells and drive the migration of GSCs to neurogenic zone." (PMID 31382985, 2019). "Chemokine (C-X-C motif) ligand 12 (CXCL12) and its receptors CXCR4 and CXCR7, which are stored in or attached to the ECM, are extremely important in forming a more invasive and resistant phenotype of glioma." (PMID 31611911, 2019). "In addition, several other chemokines are secreted by glioma cells, including monocytes chemoattractant protein-1 (MCP-1/CCL2) and stromal cell-derived factor-1(SDF-1/CXCL12)." (PMID 30413179, 2018).
glioma (continued). "In addition, CXCL12 and its receptors CXCR4/CXCR7 function by maintaining GBM stem-like cell survival and increasing glioma cell invasion." (PMID 28380429, 2017). "Furthermore, our previous studies have shown CXCL12 and MIF secreted from glioma cells to be potent chemoattractants for MC recruitment in glioma." (PMID 28445977, 2017). "Experimental and clinical evidence have indicated that the CXCL12/CXCR4 axis promotes new blood vessel formation in diverse types of malignancies, including breast, ovarian, prostate, hepatic, gastric, colorectal cancer, and glioma." (PMID 29240722, 2017). "In the context of glioma, CXCL12/CXCL12-receptor (CXCR4/CXCR7) autoregulatory signaling has been demonstrated to be important for glioblastoma survival and angiogenesis, while CX3CL1/CX3CR1 axis signaling in glioma cells controls glioma cell invasion." (PMID 28380429, 2017). "In fact, CXCL12 can activate phosphoinositide 3-kinase (PI3K)/Akt, IP3, and mitogen activated protein kinase (MAPK) pathways via CXCR4 and PLC/MAPK pathway via CXCR7, increasing cell survival in gliomas." (PMID 26880981, 2016). "Specific blockade of CXCL12 decreased MC migration by circa 32% and 20% as compared to migration towards glioma cell-conditioned medium or glioma cell-conditioned medium supplemented with non-specific IgG, respectively." (PMID 21949886, 2011). "M2 macrophages may promote tumor progression and poor prognosis by inhibiting CD8+ T cell function.Numerous studies have shown that various chemokines, including CCL2, CXCL12, LOX, MCP-3, and M-CSF, are secreted by glioma cells to attract M2 macrophages and change their phenotypes." (PMID 37766864, 2023). "However, the representative chemokines in glioma (CXCL12, CXCL16, CX3CL1, CCL2) were not significantly correlated with poor OS in the same database." (PMID 34638384, 2021). "Moreover, the dysregulation of CXCL12/CXCR4 signaling induces aberrant astrocyte proliferation, which could also contribute to glioma progression." (PMID 34084145, 2021). "Similarly, Western blotting did not reveal any differences in the tissue concentration of CXCL12 between patients with these two types of glioma." (PMID 32456359, 2020). "The ELISA results showed that FTY720 did not affect CXCL12 secretion by glioma cells, indicating that FTY720 could regulate CXCL12–CXCR4 cross-talk between microglia and glioma via decreasing the expressions of CXCR4 on the microglia." (PMID 32194542, 2020). "CXCL12, previously known as induced stromal cell-derived factor-1α, is a key signalling molecule, hypothesised to act through CXCR4/CXCR7 receptors as a chemotactic ligand for glioma cells to invade the perivascular compartment." (PMID 29113105, 2017). "Further, glioma cells expressed the MC chemotaxin CXCL12 and MCs expressed the corresponding receptor, i.e. CXCR4, suggesting that MCs could be attracted to the tumor through the CXCL12/CXCR4 axis." (PMID 21949886, 2011). "Other authors found that CXCL12 might stimulate cell migration, cell growth, and invasion of ovarian cancer cells, and that CXCR4 was found to be expressed on the majority of glioma cell lines studied and on patients' tissue samples." (PMID 18781150, 2008). "Glioma cell lines did not express CXCR3, CXCR4, CXCR6, CX3CR1, but high levels of CXCR7, which is a receptor for CXCL11 and CXCL12 and can mediate G-protein independent signals via arrestin." (PMID 26796342, 2016).
ovarian carcinoma (160 papers, 2007 to 2025). A malignant neoplasm originating from the surface ovarian epithelium. "CXCL12 expression in tumor stroma has been examined in several human cancers, including bladder, gastric and ovarian cancers, and is often associated with poor prognosis." (PMID 40849508, 2025). "Modulation of the CXCL12/CXCR4 axis in ovarian cancer has multimodal effects on pathogenesis and is associated with induction of anti-tumour immunity." (PMID 36284271, 2022). "For example, the members of the miR-200 family, miR-141 and miR-200a, target C-X-C motif chemokine ligand 12 (CXCL12; also known as CXCL12β) to regulate the immunosuppressive activity of a subtype of carcinoma-associated fibroblasts in ovarian cancer." (PMID 36428980, 2022). "We have previously shown that the enhanced production of CXCL12 in response to PGE2 exposure is associated with enhanced MDSCs accumulation in ovarian cancer microenvironments." (PMID 33809455, 2021). "Although the CRCR4/CXCL12 axis has been implicated in ovarian cancer biology, there have been limited studies on its prognostic value." (PMID 22415233, 2012). "As the CXCR4/CXCL12 pathway is involved in the metastasis of tumour cells, this has important implications for the survival of ovarian cancer patients where the main cause of death is attributed to metastasis." (PMID 22415233, 2012). "CXCL12, a chemokine produced by ovarian cancer cells, has been implicated in the control of proliferation in these cells." (PMID 21750716, 2011). "Moreover, studies in ovarian cancer also indicate an association of the CXCL12/CXCR4 axis with drug resistance." (PMID 36012171, 2022). "Furthermore, expression of the chemokine CXCR4 has been found in 59% of ovarian cancers, and CXCL12 in 91% of ovarian cancers; both have been associated with decreased disease free survival." (PMID 27213343, 2016). "High expression levels of CXCL12 in the tumor stroma have been detected in various human cancers, including gastric, bladder, and ovarian cancer through immunohistochemistry (IHC), and CXCL12 upregulation correlated with poor prognosis." (PMID 40849508, 2025). "CXCL12 was unable to induce EMT in IGROV1 CXCR4-KO, confirming the specific role of CXCR4 to promote CXCL12 mediated EMT in ovarian cancer and the ability of R54 in hinder this process." (PMID 39700131, 2024). "Cervical cancer, malignant pleural mesothelioma, ovarian cancer and renal cell carcinoma secrete CXCL12, which recruits CXCR4 expressing Tregs impaired by the specific CXCR4 antagonist AMD3100." (PMID 38704478, 2024). "CXCL12-CXCR4 axis was evaluated in human ovarian cancer cells through proliferation, migration and signaling CXCL12-dependents." (PMID 39700131, 2024). "For instance, one study has shown that the chemokine CXCL12, also known as stromal-derived factor-1 (SDF-1), is highly expressed in ovarian cancer and promotes tumor cell proliferation and invasion." (PMID 37762405, 2023). "CXCL12 is one of the most prominent chemokines fostering tumor cell survival and proliferation in models of ovarian cancer." (PMID 37564657, 2023). "The impact of CXCL12 signaling on ovarian cancer progression depends on the delicate balance between its ability to summon and activate immune cells vs. its ability to cause pathological conditions in a tumor." (PMID 37966614, 2023). "Our technical results remain to be further verified by other experimental methods to characterize regulation mechanisms like the silencing of CXCL12 in ovarian carcinoma." (PMID 37966614, 2023). "Recent evidence suggests that CXCL12 is an important immunological factor in ovarian cancer progression." (PMID 37966614, 2023). "The role of CXCR7 in EOC is poorly characterized, although the ligands, CXCL11 and CXCL12, are overexpressed in ovarian carcinomas." (PMID 35406620, 2022).